OGA (O-GlcNAcase)
Diseases named in the same sentence as OGA in open-access papers (continued):
Sharing a sentence is not in itself a finding about the gene and the disease.
cancer (continued). "Conversely, promoting O-GlcNAcylation by targeting OGA protected tumor xenografts from radiation, thus implicating O-GlcNAcylation as a key player in the DNA damage response in cancer cells and as a potential regulator of tumor radiosensitization." (PMID 31272438, 2019). "On the other hand, the OGA expression in MMTV-Neu cancer cells was higher than that in MMTV-PyVT cells." (PMID 31645543, 2019). "The OGA expression was down-regulated in MMTV-PyVT cancer cells, which was inversely correlated with the highest level of O-GlcNAcylation." (PMID 31645543, 2019). "It should be emphasized that there are several constraints in interpreting results concerning the OGT and/or OGA activity in tumorigenesis and cancer progression." (PMID 25315705, 2015). "A significant difference in expression of O-GlcNAcase gene was observed between grade 3 and grade 2 cancers (p < 0.005)." (PMID 25315705, 2015). "Subsequently, 53.3 % (8/15) pT1–pT2 tumors and 64.7 % (11/17) pT3–pT4 cancers were found to be positive for OGA." (PMID 25315705, 2015). "Despite the divergent findings regarding levels of OGT and OGA enzymes in cancers, the results of research have confirmed the carcinogenic potential of O-GlcNAc-cycling enzymes in tumor development and progression." (PMID 25315705, 2015). "Enhanced O-GlcNAcylation level corresponding to increased OGT and decreased OGA expression is commonly observed in various cancers including bone, bladder, breast, bile duct, colon, leukemia, liver, lung, ovary, pancreas, and prostate." (PMID 25426101, 2014). "Future development should certainly include detailed analysis of the regulation of the promoters of OGT and OGA, and the study of the transcription factors that control the activities of these promoters in different types of normal and cancer cells." (PMID 23964270, 2013). "Increased protein O-GlcNAcylation and changes in OGT and/or OGA expression have now been described in different cancer types including breast (30–, 32), lung, colon, liver, bladder, endometrial prostate, and chronic lymphocytic leukemia (CCL) cells." (PMID 23964270, 2013). "This review systematically examines how O‐GlcNAcylation, OGT and OGA regulate distinct phases of autophagy in cancer, and how reprogramming autophagic flux through this post‐translational modification (PTM) influences metabolic plasticity and therapy resistance." (PMID 41540817, 2026). "Modulating the cycling of OGT and OGA via pharmacological means could thus show promise in preventing the growth and metastasis of cancer cells." (PMID 37107691, 2023). "On the other hand, OGA expression was found to be lower in cancer tissues." (PMID 37110670, 2023). "Therefore, targeting O-GlcNAcylation through chemical inhibition of OGT and OGA enzymes has been proposed as an effective strategy for cancer treatment." (PMID 37689115, 2023). "Here we report the first discovery of a cancer-derived point mutation on the OGA's non-catalytic stalk domain that aberrantly regulated a small set of OGA-protein interactions and O-GlcNAc hydrolysis in critical cellular processes." (PMID 36993758, 2023). "It would be interesting to evaluate whether OGA–protein interactions also engage in modulating similar protein complexes in cancer." (PMID 36291918, 2022). "Interestingly, biochemical analyses further revealed that the interaction with FAS suppressed OGA’s catalytic activity and modulated the stress adaptation of cancer cells." (PMID 36291918, 2022). "These analyses imply a strong connection between OGT/OGA PPIs and cancer." (PMID 36291918, 2022). "Overall, these studies have begun to uncover the abnormal PPIs of OGT/OGA in cancer models." (PMID 36291918, 2022). "The first strategy is to target the enzymes OGT and OGA directly for cancer therapy." (PMID 36104770, 2022). "Third, representative examples of OGT/OGA rewired PPIs that drive cancer malfunctions." (PMID 36291918, 2022).
cancer (continued). "Notably, the same study also found that OGA was upregulated in many types of cancer and drove aerobic glycolysis and tumor growth by inhibiting pyruvate kinase M2 (PKM2)." (PMID 36291918, 2022). "Furthermore, anti-cancer drugs combined with OGA inhibition using small molecule or genetic approaches have shown synergic inhibitory effects on tumor progression." (PMID 36291918, 2022). "Thus, Hippo pathway components and O-GlcNAcylation regulatory enzymes (OGT and OGA) are potential targets for cancer diagnosis and treatment." (PMID 35740678, 2022). "Aberrant expression of OGT and OGA have been detected in many cancers." (PMID 35795059, 2022). "This knowledge will not only aid in defining the malfunctions of OGT/OGA in complex diseases such as cancer, but also facilitate the development of novel strategies to manipulate the interactions of these enzymes and a subset of proteins without global O-GlcNAc perturbation-induced side effects." (PMID 36291918, 2022). "Second, systematic analyses of OGT/OGA PPIs in cancer models." (PMID 36291918, 2022). "Homeostasis of O-GlcNAc through activities of OGT and OGA has been previously implicated in normal hematopoietic development 96, 97, in differentiation arrest of AML and Jurkat T‐cells 98 as well as in other cancers." (PMID 34646384, 2021). "Moreover, specific inhibitors of OGT and OGA are currently under development, offering promising future options for engaging metabolic regulation of cancer cell during cancer therapy." (PMID 31466420, 2019). "The clinical importance of alternations in O-GlcNAc signaling and aberrant expressions of OGT and OGA in cancer is, unfortunately, largely unknown." (PMID 25315705, 2015). "Mean expression of OGT and OGA proteins in cancer tissue were higher than in normal samples." (PMID 25315705, 2015). "However, the literature survey more often shows divergent results concerning O-GlcNAcase in cancers." (PMID 25315705, 2015). "Importantly, OGT and OGA are both correlated with survival and cancer recurrence in patients with CRC." (PMID 25000257, 2014). "Therefore, besides increased flux through the HBP, the altered expression of OGT and OGA also contributes to enhancement of O-GlcNAcylation in most cancers." (PMID 25426101, 2014). "The uncoupling of OGA expression to O-GlcNAc homeostasis could be an indicator of cancer progression and suggest that an increase of OGA protein expression would be beneficial therapeutically." (PMID 25520704, 2014). "By combining population datasets with cancer mutation databases, we identify distinct hotspot mutations with opposing clinical associations: OGT hotspot mutations correlate with improved survival in cancer patients, whereas OGA hotspot mutations are associated with reduced overall survival." (PMID 42107645, 2026). "In addition to small molecule inhibitors of OGT and OGA, several natural and synthetic compounds could reduce the proliferation of cancer cells by regulating O-GlcNAcylation modification." (PMID 41059334, 2025). "In pancreatic ductal adenocarcinoma (PDAC) cells, OGA influences the regulation of NF-κB p65 subunit and the O-GlcNAcylation of IKα and IKβ, leading to the phosphorylation of p65 Ser-536 and decreased NF-κB transcriptional activity, thus promoting cancer growth." (PMID 39487556, 2024). "Additionally, we noted a decrease in OGA expression in senescent cancer cells." (PMID 39426963, 2024). "OGT and OGA also interact with epigenetic regulators, histones, and histone-remodeling complexes and could thereby alter the expression of genes involved in tumorigenesis and cancer progression." (PMID 37107691, 2023).
cancer (continued). "Below, we highlight a few representative examples, in which the OGT/OGA–protein interactions have been validated by orthogonal methods, such as immunoprecipitation, to demonstrate the diverse molecular impacts of these PPIs on the malignant programming of cancer cells." (PMID 36291918, 2022). "The results showed that OGT and OGA expression levels changed in almost all cancers to varying degrees, suggesting that O-GlcNAcylation level and the levels of O-GlcNAc circulating enzymes might have significance for early cancer screening and prognosis." (PMID 36104770, 2022). "Moreover, high OGT expression in primary cells is associated with an adverse clinical outcome in DLCL and MM as well as CLL, although a complete picture of the role of O-GlcNAcylation requires information on OGT and OGA protein expression along with a catalogue of the cancer specific O-GlcNAcome." (PMID 34868034, 2021). "Therefore, manipulation of OGT or OGA activity might be a strategy for cancer treatment by manipulating metabolism." (PMID 28074064, 2017). "However, it remains unclear how O-GlcNAcylation and O-GlcNAc cycling enzymes, O-GlcNAc transferase (OGT) and O-GlcNAcase (OGA), affect the development of cancer in animal models." (PMID 25000257, 2014). "Interestingly, no mutations in OGT and OGA genes have been reported in human cancers, suggesting that these enzymes are tightly conserved." (PMID 25426101, 2014). "Many efforts have been made to develop therapeutic options for cancer through the manipulation of the O-GlcNAcylation of proteins, primarily using specific inhibitors of OGT or OGA." (PMID 39178944, 2024). "O-GlcNAcase (OGA) is the sole enzyme that hydrolyzes O-GlcNAcylation from thousands of proteins and is dysregulated in many diseases including cancer." (PMID 36993758, 2023). "In cancer cells, glucosamine has been reported as a substrate for protein O-GlcNAcylation by O-GlcNAc transferase (OGT), and O-GlcNAcase (OGA) can remove the O-GlcNAc modification." (PMID 37009898, 2023). "The expression of OGT promotes the growth of cancer stem cells (CSC) in colon cancer, whereas OGA inhibits this growth." (PMID 37107691, 2023). "O-GlcNAcase (OGA), which is overexpressed in many malignant tumors, can improve the proliferation of tumor cells by inhibiting PKM2." (PMID 36394009, 2022). "In general, O-GlcNAcylation activation in cancer cells can be catalyzed by O-GlcNAc transferase (OGT), whereas O-GlcNAcylation is suppressed by O-GlcNAcase (OGA)." (PMID 35795059, 2022). "Clinically relevant HBP and OGA inhibitors are already available and OGT inhibitors are in development to modulate O-GlcNAcylation as a potentially novel cancer treatment." (PMID 34868034, 2021). "In numerous human cancers, particularly in pancreatic adenocarcinoma, OGT and OGA expression levels are highly positively correlated." (PMID 31272438, 2019). "As shown by western blotting results, O-GlcNAcylated proteins levels, as well as OGA, OGT, and GFAT protein expression were much more elevated in cancer cell lines compared to the fetal cell line, in accordance with our previous study." (PMID 27252680, 2016). "We wanted to determine if inhibition of OGA, by thiamet-G in A549, and CCRF-CEM and CEM-c1 would produce an effect similar to overexpression of OGT, wherein glucocorticoid–resistant cancer cells became less resistant to glucocorticoid induced cell death." (PMID 26670328, 2015). "Targeting OGT, OGA, and HBP pathways to modulate PCD may provide a novel approach to cancer treatment." (PMID 41059334, 2025). "Furthermore, we provide evidence that artesunate exerts its antitumor effects by modulating OGA-mediated O-GlcNAcylation of ZEB1, a key transcription factor involved in cancer progression." (PMID 40771411, 2025).
cancer (continued). "In this study, we demonstrate that pharmacological perturbation of the proteasome—like that used in cancer treatment— leads to the increased abundance of OGT and OGA in a ribosome-rich fraction, concurrent with O-GlcNAc modification of core translational and ribosome-associated proteins." (PMID 39395807, 2024). "Taken together, our results suggest that ATM inhibition may promote SKOV3 cell apoptosis via suppressing hsa-miR-542-5p and elevating OGT and OGA expression, providing new insights into the application of ATM inhibitors in cancer immunotherapy." (PMID 35795059, 2022). "Deregulation of intracellular O-linked glycosylation, O-GlcNAc, as well as the enzymes involved in adding this modification to proteins (O-GlcNAc Transferase, OGT) and removing this glycosylation (O-GlcNAcase, OGA) have been described in numerous types of cancers." (PMID 35294432, 2022). "Perturbation of OGT/OGA PPI networks makes profound changes in the cell and may directly contribute to cancer malignancies." (PMID 36291918, 2022). "In conclusion, the expression patterns of OGT and OGA are diverse and have both positive and negative effects on clinicopathological features, which indicates that the role of O-GlcNAc in cancer is very complex." (PMID 36104770, 2022). "Cancer cells elevate total O-GlcNAcylation by increasing OGT and/or decreasing OGA levels." (PMID 36439421, 2022). "Many cancer types display elevated O-GlcNAcylation and abnormal OGT and OGA expression." (PMID 36439421, 2022). "Although the expression of OGT and OGA in the various cell lines was not uniformly increased or decreased, the O-GlcNAcylation level was significantly increased in all cancer cell lines compared with that in the HCoEpiC cell line." (PMID 30093632, 2019). "Thus, manipulation of O-GlcNAc levels using chemical or shRNA-mediated inhibition of OGA or OGT affects in vitro and in vivo migration/invasion of breast, lung, liver, prostate, and colon cancer cells." (PMID 23964270, 2013). "Using immunohistochemistry, the authors observed increased O-GlcNAcylation level and OGT expression in cancer tissues, whereas OGA expression level was not modified." (PMID 23964270, 2013). "Furthermore, inhibition of OGA did not potentiate glucocorticoid–induced apoptosis in several cancer cell lines." (PMID 26670328, 2015). "However, OGA level was not significantly enhanced in such cancer tissue samples." (PMID 25426101, 2014). "However, this was not the case in our cancer cell system, because the expression levels of OGT and OGA were unaffected by GFAT1 silencing." (PMID 31645543, 2019).
tumor (38 papers, 2012 to 2026). "Collectively, these results suggest that LRP1 deficiency drives tumor‐promoting activities in HCC cells by accelerating ubiquitin‐dependent degradation of OGA." (PMID 39405202, 2024). "Enhanced levels of O‐GlcNAcylation in tumor cells have been linked to cell death in pharmacological investigations of OGT or OGA inhibition." (PMID 38116061, 2023). "The results showed that higher OGT and OGA levels were associated with higher histological grades and depth of tumor invasion into the myometrium." (PMID 36104770, 2022). "The presence of a higher level of O-GlcNAcase in tumor samples was also associated with a higher tumor histological differentiation (p = 0.047)." (PMID 25315705, 2015). "The authors suggested that increased O-GlcNAc modification by OGT silencing or OGA inhibition in tumor cells may be associated with decreased E-cadherin expression and may also be linked with higher incidence of metastases in the study model." (PMID 25315705, 2015). "Patients with low OGA expression in tumors had an increasing risk of tumor recurrence after liver transplantation, indicating that OGA expression may have prognostic value for HCC." (PMID 24918087, 2014). "Collectively, these data indicate that the interplay between OGT and OGA activities finely tunes autophagic flux in a tumour microenvironment‐dependent manner." (PMID 41540817, 2026). "Combining small‐molecule inhibitors of O‐GlcNAc cycling enzymes (OGT/OGA) with autophagy modulators offers a novel strategy to overcome tumor drug resistance." (PMID 41540817, 2026). "Key tool compounds include OGT inhibitors (e.g., OSMI‐1, OSMI‐4) and OGA inhibitors (e.g., Thiamet‐G, MK‐8719), which have provided proof‐of‐concept that pharmacologically modulating O‐GlcNAcylation can alter tumour progression and autophagic flux." (PMID 41540817, 2026). "In colon cancer, GFAT inhibitors reduce O‐GlcNAcylation, suppressing mTOR activation, while OGA knockdown (KD) elevates O‐GlcNAcylation, enhancing mTOR signalling and tumour progression." (PMID 41540817, 2026). "In terms of LT, a low expression of OGA is thought to promote tumor recurrence of HCC after LT, especially in patients with low levels of alpha-fetoprotein (AFP)." (PMID 38786029, 2024). "The abundance of O-GlcNAc was elevated in HCC compared with the corresponding non-tumor sample; meanwhile, a significant reduction in OGA and unchanged OGT were detected in HCC." (PMID 34298689, 2021). "Unfortunately, a similar literature review reveals no publication describing the activity of O-GlcNAc transferase and O-GlcNAcase and their relationship with tumor aggressiveness and clinical behavior in head and neck carcinomas." (PMID 25315705, 2015). "Lynch and colleagues showed that O-GlcNAc and OGT levels are higher and OGA/OGT ratios are lower in tumor cells than in normal cells lines." (PMID 24918087, 2014). "Many authors have reported that the levels of O-GlcNAc and the protein expression of OGT and OGA are aberrant in different models, including cell lines, murine models, and human tumor samples." (PMID 24918087, 2014). "Immunochemistry analysis of patient samples showed that O-GlcNAc and OGT has the same alterations found in other tissues, with increased protein levels in tumor tissues when compared with adjacent healthy tissue, and that OGA levels appear to be unaltered." (PMID 24918087, 2014). "Overall, these findings suggest that OGA is crucial for tumor growth in CRC independently of Wnt/β-catenin signaling." (PMID 25000257, 2014). "Moreover, Thiamet-G, an O-GlcNAcase inhibitor, and 5-FU together have a synergistic inhibitory effect on tumor development." (PMID 39901036, 2025). "OGA has been reported to function as a tumor suppressor, including in HCC." (PMID 40771411, 2025). "OGA regulates tumor progression by inhibiting the O-GlcNAcylation of substrate proteins." (PMID 40771411, 2025).